MYCN (MYCN proto-oncogene, bHLH transcription factor)
Diseases named in the same sentence as MYCN in open-access papers (continued):
Sharing a sentence is not in itself a finding about the gene and the disease.
neuroblastoma (continued). "In neuroblastomas with MYCN amplification, this oncogene stabilizes the adrenergic CRC to drive the expression of its transcriptional regulatory network and enforce an immature neuroblast cell state while suppressing developmental signals that would normally induce differentiation or senescence." (PMID 34669465, 2021). "Similar to these cancers, neuroblastoma especially in MYCN-cluster might possess a tumor-specific proline vulnerability, which could be used as a target metabolic pathway for treatment." (PMID 33465163, 2021). "Surprisingly, several MYCN-amplified neuroblastomas also harbored TERT rearrangements." (PMID 34442335, 2021). "However, abnormal MYCN expression also potently sensitizes neuroblastoma cells to drug- and stress-induced apoptosis, and therefore needs to be accompanied by another collateral impairment of the cell death program to provide a tumor selective advantage." (PMID 34832966, 2021). "We, therefore, proceeded to focus our study on MYCN-amplified neuroblastoma cell lines." (PMID 33658627, 2021). "MYCN amplified neuroblastoma cells are resistant to retinoid-based differentiation therapy." (PMID 33968920, 2021). "Regarding concomitant treatment with targeted drugs and CHK1 inhibitors, we previously demonstrated that an inhibitor of ATM or DNA-dependent protein kinase (DNA-PK) potentiates CHK1 inhibitor-mediated growth suppression in MYCN-amplified neuroblastoma cell lines." (PMID 34069817, 2021). "The CDK7-dependent transcriptional addition reported in MYCN-driven neuroblastoma, triple-negative breast cancer, and pancreatic cancer is attractive because SE-associated genes are exceptionally inhibited by THZ1 so that targeting CDK7 is conducive to selective targeting." (PMID 33397398, 2021). "A recent study has found that WT1 expression is inversely correlated with MYCN expression in neuroblastoma, confirming our findings in this study, and whilst a mechanistic link is unclear, an association between high WT1 expression and poor outcome in non-MYCN amplified neuroblastomas was observed." (PMID 33918978, 2021). "We found that ALCAM, CACNA2D3, DST, EPB41L4A and KIF1B were associated with the favorable prognosis of MYCN non-amplified neuroblastoma patients." (PMID 34116676, 2021). "What has emerged in neuroblastoma and other malignancies (small cell lung cancer, rhabdomyosarcoma, Wilms' tumour, retinoblastoma, acute myeloid leukaemia, and T-acute lymphoid leukaemia) is that MYCN has a great role in dysregulating the immune network." (PMID 34195095, 2021). "Furthermore, we examined the prognostic significance of BTK expression and found that increased expression of BTK significantly correlates with worse overall survival (OS) in the non-MYCN amplified neuroblastoma cohort (Seeger dataset)." (PMID 33669187, 2021). "Quite the contrary, MYCN induces MDM2 expression in neuroblastoma cells." (PMID 34832966, 2021). "In our study, MYCN-non-amplified human neuroblastoma cells, SH-SY5Y, were quite sensitive to the HMGCR and CYP17A1 inhibitors in vitro and in vivo, whereas SK-N-BE, a MYCN-amplified human neuroblastoma cell line, were also suppressed by the two inhibitors in combination in vitro." (PMID 34041015, 2021). "Neuroblastoma is divided into risk groups based on criteria which include: the age of the patient at diagnosis, International Neuroblastoma Risk Group (INRG) tumour stage and MYCN copy number status." (PMID 33968920, 2021). "Furthermore, Alt-NHEJ was shown to be involved also in human neural crest stem cell (NCSC) neoplastic transformation by mediating MYCN pro-tumorigenic activity in neuroblastoma precursors." (PMID 33808562, 2021). "Also, the prognostic effects of age and MYCN amplification related genes in neuroblastoma were determined." (PMID 34116676, 2021). "Our results show that rigosertib might be a useful therapeutic agent for MYCN-amplified neuroblastomas, especially in combination with existing agents." (PMID 34118691, 2021).
neuroblastoma (continued). "The amplification of MYCN is related to many tumors, most notably neuroblastoma." (PMID 34642262, 2021). "Conversely, our group has demonstrated that a subset of high-risk MYCN-not-amplified (MYCNNA) neuroblastomas have increased T-cell infiltration, suggesting the presence of antigenic targets and an active anti-tumor immune response." (PMID 35464627, 2021). "As a number of ncRNAs regulate tumorigenic process downstream of MYCN, dysregulation of these transcripts might represent an alternative mechanism of MYCN up-regulation/amplification in neuroblastoma." (PMID 33718173, 2021). "Bromodomain inhibitors have specific efficacy in MYCN amplified neuroblastoma." (PMID 34116676, 2021). "In conclusion, time-resolved transcriptome analysis of early hyperplastic lesions and full-blown MYCN-driven neuroblastomas yielded novel components implicated in both tumor initiation and maintenance, providing putative novel drug targets for MYCN-driven neuroblastoma." (PMID 34638267, 2021). "This could potentially be due to intrinsic differences in protein expression and activity levels in the neuroblastoma cells and/or differential expression of known neuroblastoma oncogenes such as MYCN or ALK." (PMID 33889818, 2021). "Interestingly, MYCN is implicated in upregulation of RPL (Ribosomal Protein Large) and RPS (Ribosomal Protein Small) proteins in neuroblastoma cells." (PMID 34262099, 2021). "Of interest, a combined effect was observed by targeting GD2 ganglioside and AURKA in the inhibition of MYCN expression and induction of cell death in neuroblastoma cells Collectively, these data suggest that targeting ganglioside synthesis is a promising therapeutic strategy for liver cancer." (PMID 33803928, 2021). "They reported that expression of the ALKAL2 ligand cooperates with MYCN to drive highly penetrant and aggressive neuroblastoma growth in mice, in the absence of ALK mutation." (PMID 34885007, 2021). "Having identified novel MYCN-epigenetic links and confirmed that MYCN can interact with epigenetic genes, we next sought to identify small molecules directed against epigenetic regulators with therapeutic potential for treatment of MYCN amplified neuroblastoma." (PMID 33968920, 2021). "Further, Lamin A phosphorylation on Serine 22 is required for CDK1-catalysed nuclear envelope disassembly, and we could previously show that CDK1 is upregulated in aggressive neuroblastoma independently of MYCN status." (PMID 34771457, 2021). "MYCN amplification remains one of the most important prognostic biomarkers in neuroblastoma." (PMID 34885007, 2021). "MYCN amplification which occurs simultaneously with deletion of 1p36 may be related to chromosome 10 abnormalities in neuroblastoma." (PMID 34108028, 2021). "The cohort of neuroblastomas was highly skewed toward high-risk, and in particular, high-risk neuroblastomas without MYCN amplification." (PMID 34442335, 2021). "Together these data suggest MYCN and ALYREF bind together in a transcriptional coactivator complex to increase USP3 transcript levels, consequently reducing MYCN ubiquitination, and further increasing MYCN protein to the levels required to drive neuroblastoma tumorigenesis." (PMID 33767157, 2021). "In particular, they are characterized by a relatively low miR-204 expression with respect to non-MYCN amplified neuroblastoma cell lines, an ideal condition to investigate the effects of this microRNA not only in tumors of the sympathetic nervous system but also in neurodevelopmental conditions." (PMID 33815256, 2021). "Indeed, the effectiveness of CHK1 inhibitors in preclinical neuroblastoma and medulloblastoma models and their enhanced activity in MYCN-driven tumors has been reported." (PMID 34508175, 2021). "Similarly, MYCN (MYCN protooncogene, bHLH transcription factor) is amplified in approximately 20% of neuroblastomas (NBs) and is related to poor outcomes." (PMID 34954904, 2021).
neuroblastoma (continued). "It is now well accepted that ALK and MYCN cooperate to drive neuroblastoma." (PMID 34885007, 2021). "MYCN is an oncogenic driver in neural crest-derived neuroblastoma and medulloblastoma." (PMID 34262099, 2021). "Furthermore, studies suggest that TAMs can promote tumor progression by upregulating oncogenic MYC expression through activation of the STAT3 pathway in non-MYCN amplified neuroblastoma cells." (PMID 33917501, 2021). "Ectopic expression of MYCN inhibits retinoic-acid-induced differentiation in neuroblastoma cells." (PMID 34832966, 2021). "Ninety-six percent of the compounds reduced MYCN-amplified neuroblastoma cell viability." (PMID 33968920, 2021). "Combination of DST, age and MYCN achieved best prognostic effects in neuroblastoma." (PMID 34116676, 2021). "Overall, these data are in contrast with the neuroblastoma results and suggest a unique biology for this MYCN-driven pediatric malignancy where the AA genotype predicts a better outcome and where high ODC1 expression is consistently associated with poor outcome." (PMID 33918978, 2021). "Hence, it was assumed that upregulated expression of MYCN protein is supported by the overall downregulation of MYCN-inhibitory miRNAs in neuroblastoma." (PMID 34026620, 2021). "By contrast to BE2C and NGP cells, which became blocked in G1 phase, NBL-S and SKNAS cells treated with ATRA continued to enter S phase and progress through the cell cycle, consistent with the continued cell proliferation by these MYCN- or MYC-hijacked neuroblastoma cell lines." (PMID 34669465, 2021). "Hence, a therapy-induced decrease of MycN expression represents a promising approach for neuroblastoma therapy." (PMID 33390782, 2021). "Gene sequencing of neuroblastoma samples has revealed that the genetic makeup of up to 78% of relapsed neuroblastomas harbors new genetic mutations in the RAS–mitogen-activated protein kinase pathway (RAS–MAPK) and novel MYCN amplifications." (PMID 34777621, 2021). "Indeed, the concomitant expression of MYCN and ALKF1174L causes neuroblastoma in vivo from neural crest cells." (PMID 34680298, 2021). "We then moved to a neuroblastoma MYCN-amplified cell line, IMR-32." (PMID 34884931, 2021). "Further assessment and development of MRN inhibitors may therefore be warranted for the treatment of MYCN-amplified neuroblastomas." (PMID 34069817, 2021). "For example, future studies exploring YAP genetic knockout in the TH-MYCN transgenic mouse or MYCN amplified zebrafish models of neuroblastoma may contribute to our understanding of YAP and MYCN and their TME effects." (PMID 34572875, 2021). "In addition, we did not observe cell death induction as assessed by PARP-1 cleavage or Annexin V/PI staining, indicating differential sensitivity of neuroblastoma cell lines, depending on MYCN amplification status." (PMID 34884931, 2021). "Finally, we evaluate if trans-acting factors, in particular IGF2BP1 and ELAVL4, or a putative miRNA decoy function of the MYCN-3’UTR uncouple increased expression of MYCN-regulatory miRNAs in neuroblastoma from elevated expression of MYCN protein." (PMID 34026620, 2021). "To test the effects of retinoids on human MYCN-amplified neuroblastoma cells, we treated two MYCN gene amplified neuroblastoma cell lines (BE2C and NGP) with all-trans retinoic acid (ATRA), an active metabolite of isotretinoin, for 6 days and then examined its effects on cell growth and viability." (PMID 34669465, 2021). "Thus, MYCN activity drives a major gene expression-regulatory node which is under the control of the major neuroblastoma cell signaling pathways." (PMID 34957126, 2021).
neuroblastoma (continued). "We saw significant positive correlations between ALYREF and MYCN expression levels, as well as ALYREF copy number, further supporting ALYREF as a key intermediary in the cooperation between 17q21-ter gain and MYCN-amplification in the malignant neuroblastoma phenotype." (PMID 33767157, 2021). "In the following section, we review several approaches that could be efficacious for targeting molecules that directly contribute to MYCN-driven proliferation in neuroblastomas." (PMID 34069817, 2021). "DpC treatment significantly decreased MYC protein levels across all neuroblastoma cell lines, which suggests promising new therapy strategies, especially in MYCN-amplified neuroblastomas, which account for approximately 20% of cases and rank among those with the most difficult course of the disease." (PMID 35008802, 2021). "Amplification of the MYCN oncogene occurs in ~ 25% of neuroblastoma patients." (PMID 33497018, 2021). "This makes N-MYC an intriguing molecular target for the treatment of MYCN-amplified neuroblastomas." (PMID 35008802, 2021). "Thus, high levels of expression of either MYC or MYCN due to translocations hijacking next to the HAND2 super-enhancer produce neuroblastoma cells that are resistant to the effects of ATRA in inducing neuroblastoma cell differentiation." (PMID 34669465, 2021). "B cell infiltration could thus be used as a prognostic marker in neuroblastoma in addition to commonly utilized prognostic indications such as age, stage and MYCN amplification status." (PMID 34458583, 2021). "Kaplan–Meier curve analysis also showed that high expression of MCM genes, except for MCM9, were associated with poor survival in neuroblastoma, even in patients with MYCN-non-amplified tumor." (PMID 35056094, 2021). "Intermediate risk tumors do not have MYCN alterations, but demonstrate typical for neuroblastoma chromosomal aberrations: deletion of 11q and gain of 17q, which help to classify the tumors as type 2A." (PMID 32748156, 2021). "This suggests that this negative feed-back regulation is at least partially uncoupled in MYCN-amplified (MNA) neuroblastoma, either due to a miRNA decoy function of the MYCN-3’UTR, proposed for the let-7a miRNA, or by trans-acting factors like RNA-binding proteins (RBPs)." (PMID 34026620, 2021). "ALK mutations have been associated with poorer survival in high-risk neuroblastoma, and ALK gene is amplified in a subgroup of MYCN-amplified neuroblastoma tumors due to the proximity of the two loci (2p23-24) at the 2p-gain region associated with high-risk neuroblastoma." (PMID 34957126, 2021). "Overall, this work teased apart some of the challenges associated with understanding 1p36 loss of heterozygosity in MYCN-driven neuroblastoma, identifying the SWI/SNF chromatin remodeling complex subunit Arid1a as a MYCN collaborator that accelerates neuroblastoma onset." (PMID 34885007, 2021). "We therefore investigated whether a correlation between H2A.Z.1 and MYCN exists in neuroblastoma tumours using the R2 genomic platform." (PMID 34423893, 2021). "To test this hypothesis, we evaluated the efficacy of indisulam in an immune-competent, transgenic mouse neuroblastoma model driven by MYCN and ALKF1178L (TH-MYCN/ALKF1178L) by using ultrasound imaging to quantify tumor response." (PMID 34788094, 2021).
neuroblastoma (continued). "RNA sequencing of the MYCN-amplified NLF cells with and without YAP knockout treated with vehicle or trametinib showed that YAP mediates trametinib resistance through the transcriptional activation of E2F and MYCN, allowing the maintenance of the proliferative capacity of neuroblastoma cells." (PMID 34572875, 2021). "MYCN amplification and age are two critical prognostic factors of pediatric neuroblastoma." (PMID 34116676, 2021). "A similar functional screening assay led to development of a cancer dependency map in MYCN-amplified neuroblastoma that identified a novel protein, Nuclear Transport Factor 2 Like Export Factor 1 (NXT1, p15), that is essential for mRNA nuclear export and cellular integrity." (PMID 34944778, 2021). "In conclusion, the results of our study suggest that MYCN-amplified neuroblastomas might promote the spreading of oncogenic kinases and other biologically active proteins to the tumour microenvironment and remote body locations." (PMID 34847775, 2021). "Furthermore, age and MYCN amplification were independent prognostic factors in pediatric neuroblastoma." (PMID 34116676, 2021). "Furthermore, the multivariate cox regression assay suggested that age and MYCN amplification were independent prognostic factors in pediatric neuroblastoma in TARGET, GSE49710 and GSE85047 datasets." (PMID 34116676, 2021). "And the higher expression levels of ALCAM, CACNA2D3, DST, EPB41L4A or KIF1B were associated with better prognosis of MYCN non-amplified neuroblastoma patients." (PMID 34116676, 2021). "Amplification of the neuronal transcription factor MYCN induces malignant transformation of neuroblastoma cells and is used for disease stratification, and sensitivity of neuroblastoma cells to impaired polyamine metabolism has been demonstrated to correlate with extent of MYCN amplification." (PMID 34011385, 2021). "To validate these findings at the protein level, we performed immunoprofiling using multiplex NanoString digital spatial profiling technology on a neuroblastoma tissue array containing 33 independent neuroblastoma tumors of which 9 were MYCN.A and 24 were MYCN.NA." (PMID 34818552, 2021). "Similarly, PARP1/2 was highly expressed in MYCN-amplified neuroblastomas compared with neuroblastomas with MYCN single copy." (PMID 34069817, 2021). "In conclusion, the infiltration of naïve B cells is associated with prognosis in neuroblastoma irrespective of clinical variables and MYCN amplification status." (PMID 34458583, 2021). "Finally, cross-species master regulator analysis identified FOXM1, together with additional hubs controlling transcriptome profiles of MYCN-driven neuroblastoma." (PMID 34638267, 2021). "In 2009, International Neuroblastoma Risk Group (INRG) Task Force has proposed a system, which included age, histologic category, grade of tumor differentiation, the status of the MYCN oncogene, chromosome 11q status, and DNA ploidy as characteristics of the tumors." (PMID 32748156, 2021). "Enhanced stability of the MYCN oncoprotein is a critical driver in childhood neuroblastoma." (PMID 33658627, 2021). "Subsequent tissue-specific ALK-overexpressing mouse models have been constructed that demonstrate synergy with MYCN in the ability to generate neuroblastoma and have helped to clarify the oncogenic role of ALK, but, similarly, little is known about its physiological function." (PMID 34769149, 2021). "Literature has suggested that some compounds (e.g., 10058-F4 and 10074-G5) can inhibit MAX-MYC heterodimerization and induce growth inhibition, apoptosis, and differentiation in MYCN-amplified neuroblastoma cells, and some compounds can prolong survival of MYCN transgenic mice." (PMID 35056094, 2021). "Finally, we compared the autocrine effects induced by EVs on cell proliferation and DNA repair in SH-SY5Y and the MYCN-amplified SK-N-BE neuroblastoma cell line." (PMID 33430027, 2021).